CD46 (CD46 molecule)
Diseases named in the same sentence as CD46 in open-access papers (continued):
Sharing a sentence is not in itself a finding about the gene and the disease.
cancer (continued). "Then, we confirmed that GOS/MV-Edm entered cancer cells via the folate receptor instead of CD46, a natural cognate receptor of MV-Edm." (PMID 31533779, 2019). "Their CD46 ADC caused regression and elimination of a mCRPC cell line xenograft, showing the efficacy of targeting CD46 in combination with a tubulin inhibitor as a means to treat cancer." (PMID 31164885, 2019). "Future experiments should be performed to investigate the effects of macrophages on CD46 or CD55 expression in cancer cells and the interactions between these complement restriction factors." (PMID 31685825, 2019). "CD46 was especially overexpressed in low grade and low stage cancers, whereas its expression was reduced in later stage cancers." (PMID 30201920, 2018). "In a next experiment, cytotoxicity assays using Ad5/35-tk in combination with GCV were performed in CD46-overexpressing, CD46-suppressed, or control cells derived from all five cancer cell lines." (PMID 30201920, 2018). "CD46 utilising adenoviruses remain a popular choice for the development of oncolytic virotherapies since CD46 is upregulated in numerous cancers, though CD46 is far from unique to cancer as it is present on the surface of all nucleated cells." (PMID 29904022, 2018). "CD46 is generally overexpressed in many human cancers, representing a prime target for CD46-binding adenoviruses (Ads)." (PMID 30201920, 2018). "Results demonstrated the ability of virus to infect cancer cells which can be attributed to expression of CD46 and nectin-4 receptors in cancer cells." (PMID 30697531, 2018). "Overexpression of the membrane-associated C regulatory proteins (mCRPs) CD46, CD55, and CD59 is another mechanism by which cancer cells can evade undesired C attack due to spontaneous or Ab-induced C activation." (PMID 30319647, 2018). "CD46 was abundantly expressed in all five cancer cell lines, revealing multiple isoforms due to alternative splicing and polyadenylation." (PMID 30201920, 2018). "Alternatively, species B Ads, which utilize several host cell receptors including CD46 (Ad3/11/35) and desmoglein-2 (Ad3/7/11/14), have been employed to provide more effective cancer targeting." (PMID 30201920, 2018). "Three forms of CD46 exist in normal individuals and cancer patients, with molecular masses of 56, 47, and 29 kDa." (PMID 28273946, 2017). "EnAd infects cells by binding to CD46 and/or desmoglein 2,6 both widely expressed on many carcinoma cells." (PMID 28345021, 2017). "Despite a limited knowledge on the expression status of many cancer cells, an increasing number of cancer gene therapy studies include fiber-modified Ad vectors redirected to the more ubiquitously expressed CD46." (PMID 27203670, 2016). "Although CD46 is also upregulated on many tumors, it is less useful as a target for cancer therapy, since normal human cells express this protein on their surfaces." (PMID 27657109, 2016). "In fact, chimeric Ad5/35 vectors targeting CD46 are known to be better tools than vectors targeting CAR for cancer targeted gene therapy." (PMID 27203670, 2016). "Despite the increasing number of cancer therapeutic approaches using these chimeric adenoviral vectors, the detailed expression status of CD46 as a viral target in human cancers remains to be elucidated." (PMID 27203670, 2016). "It has been reported that the effectiveness of MV-Edm-mediated oncolysis is dependent upon the expression of the cellular attachment receptor CD46 which is more frequently over-expressed in human cancer cells than in normal cells." (PMID 25909216, 2015). "Actually, CD46 is frequently overexpressed on human cancer cells and barely expressed on normal cells (such as, fibrocytes and lymphocytes)." (PMID 25909216, 2015). "Secondly, CD46 is expressed at low levels on all nucleated cells and is upregulated in numerous cancers (breast, cervical, colorectal, gastrointestinal, lung, leukemias and multiple myelomas)." (PMID 24892636, 2014).
cancer (continued). "Attenuated vaccine strains of MeV can preferentially infect cancer cells expressing higher densities of CD46 molecules on their surface." (PMID 24892636, 2014). "The effectiveness of MV-Edm-mediated oncolysis is highly dependent upon the expression of the cellular attachment receptor CD46, which is expressed more frequently in human cancer cells than in normal cells." (PMID 23009685, 2012). "We thus hypothesize that CD46/TREM1 may contribute to the inflammation-cancer transformation in OSCC by activating the PI3K-AKT-mTOR pathway and subsequently inhibiting autophagy, as indicated by downregulated LC3B/ATG5." (PMID 41415031, 2025). "Additionally, high concentrations of soluble CD46 (that remain functional) have been observed in the sera of patients with cancer." (PMID 40309774, 2025). "Another approach uses viruses that target cancer cell markers, such as CD46; tumors frequently express this molecule to evade complement-mediated immunity, allowing the measles virus (Edmonston strain) to infect cells via CD46 and selectively kill cancer cells with high receptor expression." (PMID 41294877, 2025). "Herein, we review CD46 and its “multiverse” of cancer interactions." (PMID 40309774, 2025). "Thus, the role of CD46 as a metabolic driver points to its involvement in malignant transformation and/or cellular proliferation, especially because cancer cells are known to be highly glycolytic and to anaerobically metabolize glucose." (PMID 40309774, 2025). "The neutralizing antibodies suppressed viral accumulation in the lungs by about 10-fold in human CD46-transgenic mice without loss of infectivity to cancer cells." (PMID 40561062, 2025). "Thus, modified viral vectors (such as strains of adenovirus and measles virus) targeting CD46 currently are being exploited against a wide range of cancers." (PMID 40309774, 2025). "CD46 may play a key role in the immune response to cancer cells, and elucidating its role in carcinogenesis would be helpful for the treatment of cancer." (PMID 38919630, 2024). "Downregulation of CD46 expression by small interfering RNA (siRNA) could sensitize cancer cells to complement attack in vitro." (PMID 38919630, 2024). "To overcome the low expression of the Ad5 binding receptor coxsackievirus and adenovirus receptor (CAR) by cancer cells and improve infectivity, we equipped the virus with an Ad5/Ad3-modified fiber, which allows for CD46 and desmoglein 2 (DSG2) receptor attachment." (PMID 38675909, 2024). "CD46 staining was more pronounced in cancer cells than in stromal cells in situ (in tissues)." (PMID 38919630, 2024). "Therefore, further detailed research in our future studies are needed to clarify the mechanism of action of CD46, and its application in cancer treatment." (PMID 38919630, 2024). "CD46 has been revealed to be a key factor in malignant transformation and cancer treatment." (PMID 38919630, 2024). "Notably, CD46 expression in normal tissue is low, and it would be a suitable target for cancer immunotherapy." (PMID 35924232, 2022). "However, attenuated MV particles are capable of using CD46 as a cell entry receptor, which is a regulator of complement activation abundantly presented on cancer cells." (PMID 36140243, 2022). "The MTT in vitro proliferation assay was first performed to determine whether CD46 overexpression can modulate the growth of cancer cells through modulating immunologic response." (PMID 36575233, 2022). "Because CD46 plays a crucial role in metabolic changes during T cell activation and metabolic reprograming is critical for cancer cell survival, it is conceivable that similar mechanisms may operate in cancer cells." (PMID 35860237, 2022). "Similar to HLA-G, CD46 was found to be upregulated in a variety of cancer cells." (PMID 35924232, 2022). "The results presented here indicated that the cetuximab-mediated inhibition of CD46 expression might be a beneficial action mechanism in mAb immunotherapy for cancers." (PMID 36575233, 2022).
cancer (continued). "While treatment of cancer cells with cetuximab caused the downregulation of CD46 and CD59, the overexpression of CD46 protected the cells not only from direct effects via ADCC and CDC but also through indirect effects." (PMID 36575233, 2022). "Thus, vaccine-lineage MeV is currently being evaluated in clinical trials as a CD46-targeted therapeutic agent for cancer treatment." (PMID 33534834, 2021). "It has been reported that MM, as other cancer cells, overexpress CD46 compared to normal cells." (PMID 33668361, 2021). "CD46 expression is low or moderate in most normal tissues, but upregulated in many types of cancer." (PMID 32957644, 2020). "We hypothesize that CD46 isoform cytoplasmic tail switching (as occurs in activated versus quiescent T cells) may be altered in cancers, such as MM." (PMID 33147799, 2020). "One reason for the upregulation might be that CD46 can protect cancer cells from being killed by the complement system." (PMID 32957644, 2020). "Notably, a body of literature, as well as online resources such as The Cancer Genome Atlas (TCGA) Program reveal that the involvement of CD46 in cancer varies." (PMID 33147799, 2020). "Thus, by suppressing C3 deposition on the cancer cells, CD46 and CD55 can lower, on one hand, the extent of MAC generation and CDC, and on the other hand, reduce immune protection through complement-dependent cellular cytotoxicity." (PMID 31024572, 2019). "However, because of scarce side-by-side information about CAR and CD46 expression levels in cancer cells, mixed observations of cancer therapeutic efficacy have been observed." (PMID 30201920, 2018). "The surface expression levels of human CD46 we could achieve, even in clonally-selected cells, were lower in murine cells transduced with a lentiviral construct containing CMV-driven human CD46 gene compared to endogenous expression in A549 human cancer cells." (PMID 29898782, 2018). "Therefore, Ad-based cancer gene therapies targeting overexpressed CD46 have been suggested to enhance the antitumor capability, and to improve the gene transduction efficiency." (PMID 30201920, 2018). "It has been proposed that overexpression of CD46 may serve to protect cancer cells from complement-dependent cytotoxicity, thereby evading destruction caused by the immune system." (PMID 27203670, 2016). "Generally, CD46 expression was higher in most cancer cells compared to CAR expression." (PMID 27203670, 2016). "Live-attenuated vaccinal strains of measles virus (MV) are of particular interest due to their ability to specifically target different types of human tumors through recognition of the CD46 membrane complement regulatory molecule which is frequently overexpressed on cancer cells." (PMID 23586034, 2013). "Should the complement cascade override the effects of CD55 (and CD46, another mCRP) and manage to activate the terminal complement components on cancer cell membranes, functional CD59 molecules bind to human C8 and C9, during the attempt to properly assemble the membrane attack complex." (PMID 17623109, 2007). "Moreover, CD46 has recently emerged as a key player in cancer biology." (PMID 40309774, 2025). "CD46 may well become part of the established arsenal of key players in cancer therapeutics." (PMID 40309774, 2025). "Therefore, CD46 might pose a valuable receptor for targeting of cancer cells as well as CAFs in PDAC." (PMID 38037840, 2024). "Furthermore, after therapeutic monoclonal antibody (mAb) treatment, downregulation of CD46 expression in cancer cells could enhance the CDC effect and improve therapeutic outcomes." (PMID 38919630, 2024). "However, the role of CD46 in these cancers is not clearly understood." (PMID 36575233, 2022). "Therefore, advanced cancers are frequently characterized by high levels of CD46." (PMID 33291506, 2020). "This might be due to the protective function of CD46 or CD55 on cancer cells." (PMID 31685825, 2019).
cancer (continued). "In addition murine CD46 is restricted predominantly to testicular cells, therefore, it is unlikely that murine CD46 could serve as a receptor for human adenoviruses in most cancer cell types." (PMID 29898782, 2018). "The immunohistochemistry results showed that the expression of CD46 and TREM1 in cancer tissues was significantly higher than that in normal mucosa and inflammatory tissues (P < 0.01)." (PMID 40475017, 2025). "We found cancer stem cell gene, CD24 (logFC = 0.9), and therapy resistant genes, CD46 (logFC = 0.3) and CD55 (logFC = 0.4) expressed in ES1, ES2, and ES3 combined, compared to ES0, and cancer stem cell marker, CD59 to be the highest in ES1 (logFC = 0.4)." (PMID 38328306, 2023). "When cancer cells exhibit high numbers of specific viral receptors, such as CAR, CD46, or CD155, OVs have the potential to infect, multiply, and destroy the cancer cells." (PMID 37880659, 2023). "Low expression of terminal elements (C8A, C8B, and C9) was detected in all cancer types, whereas complement regulators (C1inh, FH, FI CD46, CD55, and CD59) are highly expressed in most cancers." (PMID 38003705, 2023). "Overexpression of CD46 protected the cancer cells from both CDC and ADCC, suggesting that the EGFR-targeted anticancer agent cetuximab downregulated the expression of CD46 to maximize the cell-killing activity, thereby affecting both CDC and ADCC." (PMID 36575233, 2022). "Inhibition of complement activation via the overexpression of complement-regulatory proteins (CRPs), most notably CD46, CD55 and CD59, is an efficient mechanism of disguise of cancer cells from a host immune system." (PMID 35563599, 2022). "In this study, cetuximab inhibited the expression of CD46 and CD59, but stimulated that of CD55, thereby protecting cancer cells from both CDC and ADCC." (PMID 36575233, 2022). "Overall, our data provides evidence that the variables without CD46 are suitable for diagnostic patients with grade 1 iCCA and superior for prognosticating with the grade 1 iCCA and the grade 1 HCCs, and can also be appropriate for cancer grade 2/3 iCCA/HCCs patients." (PMID 34208132, 2021). "Species B Ads pose interesting candidates for oncolytic therapy as their receptors, CD46 and DSG-2, are often upregulated in cancer." (PMID 32957644, 2020). "Recently, CD46 (membrane cofactor protein; MCP) has emerged as a key player in both malignant transformation as well as in cancer treatments." (PMID 33147799, 2020). "Ad5 vectors with the chimeric Ad5/3 fiber knob modification, including ONCOS‐102, are thought to use both CD46 and DSG2 to bind to and infect cancer cells." (PMID 31944306, 2020). "Understanding the role of CD46 in HCC development is important for the development of effective means of prevention and treatment of this highly malignant form of cancer." (PMID 24297460, 2014). "Cancer cells, in particular, possess membrane complement regulatory proteins (mCRPs such as CD46, CD55 and CD59) on their surfaces to ultimately thwart MAC pore formation and only allow for about 50%–60% cancer cell kill rates in vitro." (PMID 24276022, 2013). "Meanwhile, CD55 and CD46 on malignant cells restrict deposited C4b and C3b, and CD59 inhibits complement membrane attack complex formation, therein protecting cancer cells from membrane damage." (PMID 17623109, 2007). "Since there is an ever-going debate as to whether the complement system is pro- or anti-cancer, we aimed in the current study to investigate the expression pattern of two important complement regulatory proteins; CD46 and CD55 in ALL and AML cancer patients." (PMID 41526546, 2026). "The results showed that CD46 and TREM1 genes were overexpressed on the surface of cancer tissues." (PMID 40475017, 2025). "Knockdown of CD46 activated OSCC autophagy and promoted cancer cell apoptosis." (PMID 40475017, 2025).
cancer (continued). "Overall, these studies highlight the critical roles of IL6 and IL6R, as well as CD46 and JAG1, in the survival and invasive capacity of cancer cells, and their broad promise as targets for antitumor therapies, as well as exploring the possibility of combining them with other therapeutic agents." (PMID 38571938, 2024). "Nevertheless, it seems that the absence of CD46 strongly reduces GoraVir's ability to infect and kill these cancer cell lines." (PMID 38037840, 2024). "Regarding infectivity, cancer cells may also overexpress different surface receptors, such as CD46, ICAM-1, CD55, CD155 or integrins, allowing OVs to infect cancer cells." (PMID 35493490, 2022). "Removal of GPI-anchored proteins, which include the complement-regulatory proteins CD59 and CD55 but not CD46, with PI-PLC treatment resulted in enhanced susceptibility of cancer cells to complement lysis." (PMID 35227072, 2022). "However, previous studies have reported a significant downregulation of membrane-bound complement regulators (CD46, CD55, and CD59) in SCLC compared to other cancers, including NSCLC." (PMID 34996345, 2022). "Moreover, lymph cells highly express other signaling pathways that can be ultimately connected to interactions between cancer cells and T cells, such as APP, CD99, MHC-I, and CD46." (PMID 34830900, 2021). "It has been hypothesized that cancer cells escape from complement system by activating complement inhibitors, such as CD59, CD46, and CD55." (PMID 32922663, 2020). "Interestingly, cancer cells produce high levels of complement inhibitors, such as factor H, CD55 and CD46, and therefore therapeutics have to be carefully chosen for disease specific targeting." (PMID 32923410, 2020). "Moreover, the membrane-bound complement regulatory proteins (mCRPs), including MCP (CD46), DAF (CD55), and CD59, have been found overexpression in many cancer cells." (PMID 33614473, 2020). "Upregulation of CD46 and CD55 protects cancer cells from complement-dependent cytotoxicity, and the inhibition of these targets may be used as a strategy to enhance the effect of anticancer antibodies, like trastuzumab in HER2+ BC." (PMID 33007869, 2020). "In addition, the expression of membrane-bound complement regulatory proteins (mCRPs), including CD46, CD55 and CD59, is upregulated in many types of cancer cells, which can dwarf antitumor therapeutic efficacy." (PMID 31787848, 2019). "In addition, the targeting of mCRPs, such as CD46 and CD59, for cancer immunotherapy has recently been explored." (PMID 31787848, 2019). "Currently, the molecular mechanisms leading to differential expression of CD46 during cancer cell progression is not understood." (PMID 30201920, 2018). "It is speculated that CD46 and TREM1 may inhibit autophagic apoptotic genes LC3B and ATG5 by mediating the activation of the inflammatory cancer chain, thus weakening the apoptotic signal and leading to the proliferation and escape of cancer cells." (PMID 40475017, 2025). "Furthermore, we identified several significantly upregulated genes (CD46, JAG1, IL6, and IL6R) that may positively correlate with cancer cells' survival and invasive capabilities in this subtype." (PMID 38571938, 2024). "Like all normal cells, cancer cells are protected from autologous complement attack by several specific cell-surface complement inhibitors: CD55 (decay accelerating factor, DAF), CD46 (membrane cofactor protein, MCP), CD59, and CD35 (complement receptor type 1, CR1)." (PMID 31024572, 2019). "It has been reported that CD46, CD55 and CD59 could protect cancer cells from MAC-mediated CDC." (PMID 31787848, 2019). "Additionally, several different complement-regulatory proteins (CRPs) function to inhibit complement activation, and certain membrane-bound CRPs such as CD46, CD55, and CD59 were reported to be aberrantly expressed in various cancers, which likely confers resistance to CDC." (PMID 29354121, 2017).